LINC02298 (long independently transcribed non-coding RNA 2298)
Synonyms: LOC124903398
Gene: Long non-coding RNA gene on chromosome 14 (105,032,855 to 105,101,973, forward strand). Ensembl gene ENSG00000257556.
Diseases named in the same sentence as LINC02298 in open-access papers:
LINC02298 is named in the same sentence as 1 disease in open-access papers, as found by Europe PMC text mining. Sharing a sentence is not in itself a finding about the gene and the disease. The quoted sentences say what the papers report.
cancer (1 paper, 2022). A tumor composed of atypical neoplastic, often pleomorphic cells that invade other tissues. "In addition, the specific roles and mechanisms of LINC02298, AP000851.2, and AL162274.1 in cancer have not been fully elucidated." (PMID 35837104, 2022).